HUS1B (HUS1 checkpoint clamp component B)
Tractability: No criterion of Open Targets' tractability assessment is met for any kind of drug.
Gene: Protein-coding gene on chromosome 6 (655,939 to 657,100, reverse strand). Ensembl gene ENSG00000188996.
Subcellular location (Human Protein Atlas): Nucleoplasm; Cytosol
Gene Ontology:
Biological process: double-strand break repair via homologous recombination; meiotic DNA integrity checkpoint signaling; mitotic DNA replication checkpoint signaling; mitotic intra-S DNA damage checkpoint signaling; nucleotide-excision repair; telomere maintenance; DNA damage checkpoint signaling; DNA metabolic process
Cellular component: checkpoint clamp complex; site of double-strand break; nucleolus
Genetic constraint (gnomAD): Loss-of-function variants: 1 observed, 0.54 expected, observed/expected ratio (o/e) 1.85, 90% interval 0.34 to 1.93. That is too few expected variants to judge how well the gene tolerates losing a copy. Missense variants: 460 observed, 366.28 expected, observed/expected ratio (o/e) 1.26, 90% interval 1.16 to 1.36. Synonymous variants: 201 observed, 163.39 expected, observed/expected ratio (o/e) 1.23, 90% interval 1.1 to 1.38.
Homologues: Orthologues: mouse Hus1b (64% identical), zebrafish HUS1 (49% identical), tropical clawed frog hus1 (44% identical), Drosophila melanogaster Hus1-like (27% identical), Caenorhabditis elegans hus-1 (22% identical). Paralogues in human: HUS1 (49% identical).
Diseases named in the same sentence as HUS1B in open-access papers:
HUS1B is named in the same sentence as 1 disease in open-access papers, as found by Europe PMC text mining. Sharing a sentence is not in itself a finding about the gene and the disease.
HUS1B shares sentences with these, for which no sentence is quoted: cancer (2 papers).